CXCL10 (C-X-C motif chemokine ligand 10)
Diseases named in the same sentence as CXCL10 in open-access papers (continued):
Sharing a sentence is not in itself a finding about the gene and the disease.
tumor (continued). "The traditional concept is that CXCL10/CXCL9 largely produced at the tumor site is associated with directing the migration of CXCR3+ effector CD4+ and mostly effector -cytotoxic CD8+ T cells, and CXCR3+ NK cells to the tumor site." (PMID 34944943, 2021). "We co-cultured tumor cells with different CXCL10 interference with T cells and found that overexpression of CXCL10 can effectively enhance tumor suppression and apoptosis caused by T cells, and this phenomenon was reversed when CXCL10 was inhibited." (PMID 34794429, 2021). "The literature has indicated that immunotherapy targeting PD-1 and CTLA-4 specifically increases CXCL9 and CXCL10 from tumor-associated macrophages in tumor tissues, whereas CXCL9 and CXCL10 are induced by IFNγ in the tumor microenvironment." (PMID 34680466, 2021). "Elevated levels of the chemokines, such as CXC-chemokine ligand 9 (CXCL9) and CXC-chemokine ligand 10 (CXCL10) are reportedly associated with the increased number of tumor-infiltrating CD8+ T cells." (PMID 33809707, 2021). "Loss of CXCR3 or its ligands, CXCL9 or CXCL10, has been shown to disrupt the migration of adoptively transferred T cells to solid tumors resulting in impaired anti-tumor responses." (PMID 34867942, 2021). "CXCL9 and CXCL10 had functions in the tumor microenvironment, such as regulating T cell differentiation and directing the migration of immune cells to tumor tissues, while CCL5 was thought to be associated with graft-versus-host disease." (PMID 34727927, 2021). "Through the intersection of difference and correlation analyses, 3 kinds of tumor-infiltrating immune cells were negatively associated with the expression of CXCL10 which included memory B cells, regulatory T cells (Tregs), and macrophages M0." (PMID 33681290, 2021). "As a pro-inflammatory chemokine, CXCL10 was found to be closely associated with multiple inflammatory diseases such as immune dysfunction, infectious diseases and tumor development." (PMID 34481469, 2021). "Further analysis revealed that TMB, neoantigen load and tumor infiltrating immune phenotype were significantly elevated in tumors with high expression of CXCL10, which was closely linked to immunotherapeutic efficacy." (PMID 34158843, 2021). "In line with this, Methylobacterium adhaesivum was associated with the high expression of CXCL10 in tumor tissues." (PMID 34539647, 2021). "Cutaneous tumor control was also lost when mast cell-deficient mice were reconstituted with Cxcl10-deficient mast cells." (PMID 33922465, 2021). "Along with this an accumulating number of studies showed in various human cancers a clear association between poor prognosis and low expression of CXCL10 at tumor sites, and vice versa." (PMID 32547545, 2020). "It was inferred that CXCL10 is negatively associated with tumor purity and positively related to dendritic cells and neutrophil." (PMID 33240622, 2020). "As predicated by bioinformatics, miR-588 directly targeted CXC chemokine ligand 5 (CXCL5), CXCL9, and CXCL10, which are associated with tumor-infiltrating immune cells in GC." (PMID 33323542, 2020). "CXCL10 expression is negatively associated with tumor purity (r = − 0.493, p = 9.16E−04) and positively associated with the infiltration levels of neutrophil, and dendritic cell." (PMID 33240622, 2020). "Herein, the mTOR cascade in both tumor cells and T cells were likely to associated with CXCL10-mediated T cells chemotaxis and anti-tumor effect." (PMID 32483450, 2020). "For example, upregulation of CXCL9 or CXCL10 is associated with increased tumor infiltrating CD8+ T cells and natural killer cells." (PMID 33062639, 2020). "Conditional deletion of miR-21 in macrophages reduces tumor growth by promoting CTL activity and diminishing the proliferative phenotype of tumor-associated vasculature via increased IL-12 and CXCL10 production." (PMID 31710308, 2019).
tumor (continued). "Upregulation of glycolysis pathway genes was linked to decreased T cell attraction through CXCL10, less tumour infiltration, and an impaired CTL effector phenotype in melanoma and NSCLC." (PMID 30232514, 2019). "Expression levels of CXCL10 have been associated with inflammatory diseases including infectious diseases, immune dysfunction, and tumor development." (PMID 30242057, 2018). "In another study, STAT3 signaling in CD8+ T cells was shown to downregulate IFNγ production, leading to decreased CXCL10 expression by tumor-associated macrophages." (PMID 30319622, 2018). "Several studies have also shown that CXCR3 expression on T cells, or expression of CXCL9 and CXCL10 in tumor tissue, is associated with increased TIL accumulation and a favourable clinical outcome in CRC." (PMID 29671006, 2018). "CXCL10 20 was usually associated with the process from tumor occurrence, development and therapy to prognosis of cancer." (PMID 28176846, 2017). "In this study higher concentrations of CXCL10 in the tumor tissue were associated with adverse prognosis." (PMID 28537901, 2017). "Lower levels of CCL11 (Eotaxin-1) and CXCL10 (IP-10) in the tumor tissue were associated with a better prognosis (p = 0.022; p = 0.002)." (PMID 28537901, 2017). "Previously, we demonstrated that pro-inflammatory chemokines CXCL9 and CXCL10 were associated with an increase in tumor infiltrating CD8+ T cells." (PMID 27369431, 2016). "High levels of CCL5/RANTES (a CCR5 ligand) and CXCL9/MIG and CXCL10/IP10 (ligands for CXCR3) in tumor tissues are associated with increased infiltration of cytotoxic effector T cells (Teff)." (PMID 26087182, 2015). "In a multivariate logistic regression model, correcting for gender, age, size of tumour and nodal-status, CXCL10 expression was again significantly associated with response to radiation therapy (p = 0.05)." (PMID 24395654, 2014). "In all of the patient biopsies, CD68-positive tumour-associated macrophages presented a mixed CXCL10 (M1)/CD163 (M2) pattern, expressed CXCR4, GM-CSF and HB-EGF, and some stained positive for CXCL12." (PMID 20946648, 2010). "In addition, a positive correlation was observed between CXCL10 expression and the inferred abundance of tumor-infiltrating lymphocytes (TILs), suggesting that higher CXCL10 levels are linked to a more immunologically active tumor microenvironment." (PMID 41463372, 2025). "Presence of TLS in HGSOC tumors associated with B cell maturation & cytotoxic tumor-specific T cell activation & proliferation.Copy-number loss of IL15 & CXCL10 may limit TLS formation in HGSOC." (PMID 40475770, 2025). "Notably, it has been reported that the expression of these chemokines, specifically CXCL9 and CXCL10, is upregulated in the tumor microenvironment of METTL3-deficient tumors." (PMID 39497707, 2025). "In addition, there is increasing evidence that Cxcl10 plays a tumorigenic role, causing tumor progression and metastasis in different cancers." (PMID 40282557, 2025). "Overexpression of CXCL10 may instead contribute to the recruitment and activation of immunosuppressive cell subsets, including Tregs, MDSCs and M2-polarized tumor-associated macrophages." (PMID 40760734, 2025). "CXCL9 and CXCL10 were associated with increased tumor infiltrating CD8+T cells." (PMID 40242222, 2025). "In line with this, our data from a Phase I clinical trial testing a novel chemo-immunotherapy combination show that increased loco-regional CXCL10 secretion serves as a hallmark of type 1, (interferon-induced) anti-tumor immune response, with beneficial roles in the immune TME." (PMID 40642792, 2025). "Notably, a recent study found a decrease in CXCL10 concentrations associated with timing of tumor progression." (PMID 39775044, 2025). "Interestingly, we discovered that PRMT5 deficiency led to a decrease in CXCL10 expression in tumor cells." (PMID 41463372, 2025).
tumor (continued). "Moreover, a prospective cohort study showed that high serum CXCL10 levels were associated with increased tumor burden, suggesting its potential utility as a biomarker." (PMID 41476984, 2025). "However, SFRP2, SPINK1, CXCL11, CXCL13, and CXCL10 exhibited gene copy loss in certain tumor populations." (PMID 38577604, 2024). "In addition, the presence of circulating tumor cells (CTCs), circulating tumor DNA (ctDNA), and changes in the abundance of some proteins (CXCL10, ASPH, SPP2, ENO2, etc) all predicted the risk of postoperative recurrence 8-12." (PMID 39430252, 2024). "IRI also affects tumour cell invasion and migration through modulation of cell motility regulators and the activation of the CXCL-10 pathway, which causes the recruitment of progenitor cells, creates a pro-angiogenic environment, and suppresses immune responses against tumours." (PMID 38920705, 2024). "Our study suggests a tumor load-dependent inflammatory circuit in MM with the release of CXCL10 from myeloid cells causing the migration of CXCR3 + inflammatory T cells from the periphery to the BM, in line with previous reports in the context of cancer and vaccinations." (PMID 39613747, 2024). "Furthermore, immunosuppressive macrophages from patients with ErbB-mutated gallbladder cancer up-regulated the expression of CXCL10, which in turn favored the interaction with Treg cells, thus disabling anti-tumor immune activity." (PMID 39596815, 2024). "Interestingly, the authors identified a cytokine signature consisting of downregulation in IL-2/IL-16/CXCL10 as associated with tumor resistance." (PMID 38339310, 2024). "Interestingly, CXCL9 and CXCL10 produced by tumor-associated macrophages (TAMs) have also been correlated with enhanced anti-programmed death-ligand 1 (PD-L1) response rates." (PMID 39596815, 2024). "Finally, the risk score was calculated by the following formula: tumor-associated endothelial signature score = 0.180855332*ADD1 + 0.059530341*ALOX12 + 0.145361104 *CXCL10 - 0.081730252*F2RL1 + 0.001225741*ITGAX − 0.004914148*MET." (PMID 37719845, 2023). "Furthermore, CXCL10 expression in tumor tissues has been reported to be strongly associated with responses to ICB therapy, which is consistent with our results." (PMID 37082269, 2023). "Notably, upregulated PD-L1 on tumor cells caused by MFAP5_OE CAFs was also partially reversed when CXCL10 was blocked in vivo." (PMID 37156839, 2023). "It cannot be excluded that the increase in CXCL10 may be the consequence of a systemic proinflammatory state linked to the presence of tumor which in turn leads to the recruitment of lymphocytes and induces a local response with an increase in chemokines." (PMID 36984881, 2023). "Furthermore, the genetic inactivation of Cxcl10 mediated an alteration of the tumor-associated immune response and modified chemokine/chemokine receptor networks." (PMID 35897689, 2022). "In addition, increased Cxcl10 expression is inversely correlated with tumor growth and is associated with cardiac allograft rejections in the PNS, such that enhanced systemic Cxcl10 expression is a prognostic biomarker of graft-versus-host disease." (PMID 35986378, 2022). "Studies showed that CXCL9 and CXCL10 may cause functional NK cell deficiencies and lead to deterioration of the tumor microenvironment of cHL." (PMID 35452413, 2022). "Additionally, IRF1 has also been implicated in the regulation of CD8+ T-cell infiltration in tumours by mediating the expression of the chemokine CXCL10." (PMID 36010935, 2022). "Furthermore, the chemokines CXCL9 and CXCL10 that are greatly implicated in the recruitment of CD8+ T cells to tumor were also upregulated after the treatment with anti-PD-1 antibody, and were further increased in response to the combined treatment." (PMID 35738798, 2022). "In addition to induction of Th1 and NK cells, CXCL10 has been associated with the recruitment of CXCR3(+) CD8(+) T cells to the tumor site." (PMID 35408440, 2022).
tumor (continued). "Consequently, the deletion of Cxcl10 not only changes the immune cell repertoire and the tumor-associated inflammatory tumor microenvironment, but also impacts the overall chemokine/chemokine receptor network during hepatic carcinogenesis." (PMID 35897689, 2022). "Furthermore, the DEN/CCl4-treated Cxcl10−/− mice showed a reduced tumor-associated angiogenesis and an altered EMC/tumor stroma composition." (PMID 35897689, 2022). "Gene intersection and survival analysis showed that there were 435 DEG crosses in PTC patients and genome-wide tumor samples, only CXCL10, CD40LG, KRT14, TRAT1, and TREM2 were associated with patient prognosis, and TCGA showed that only the TREM2 expression was upregulated in PTC." (PMID 36438899, 2022). "For example, the presence of CXCL10 or CXCL11 within the tumor is associated with a CD8 T-cell number but also with the CD4 Treg cell accumulation with immunosuppressive and cancer-initiating effects, thus rendering it difficult to use such chemokines as prognostic factors." (PMID 36429101, 2022). "Next, we evaluated whether this association between the genetic deletion of Cxcl10 and tumor-associated angiogenesis is a statistical phenomenon or whether a functional relationship exists between these parameters." (PMID 35897689, 2022). "Furthermore, we used immunohistochemistry to detect the overexpression of CXCL10 in tumor models and found that overexpression can cause more cytotoxic T cells to infiltrate the tumor tissue." (PMID 34794429, 2021). "In addition, CXCL10 was predominantly expressed by tumor associated macrophages and its receptor CXCR3 was highly expressed in T cells at the single-cell level." (PMID 34276760, 2021). "Moreover, CXCR3, the receptor for CXCL10, is found to show over-expression within many malignant tumors, which has tumor growth-promoting activity and is associated with dismal survival and metastasis of many cancers 29,62-64." (PMID 34345201, 2021). "Additionally, tumor-associated macrophages (TAMs) characteristic cytokines such as CXCL10 and CXCL11 were significantly differentially expressed." (PMID 34552581, 2021). "Based on these findings, we believe that in Tu‐Sk.T6Tg mice, over‐expressed SIRT6 might have reduced tumour growth and associated muscle wasting via downregulation of secreted CXCL10 and preservation of plasma level of insulin." (PMID 34212132, 2021). "We first assessed several human macrophage cell lines, which all responded to IFNγ by upregulating NAMPT expression, in parallel with the positive control IFNγ target CXCL10, leading us to investigate a role for this metabolic enzyme in regulating human tumor-associated immune responses." (PMID 33976173, 2021). "Moreover, the strong expression of CXCL9 and CXCL10 within tumour tissues is also associated with high CD8+ T cell infiltration in melanoma patients." (PMID 33809369, 2021). "To explore the association between DEX inhibited-tumor growth and accumulation of immune response-related cells, we measured the levels of Cxcl9, Cxcl10, Cd3e, Gzmb, and Ifng which are closely related to the recruitment, presence, and function of Th1 cells and CD8+ T cells in the TME." (PMID 32156004, 2020). "Moreover, in human cancers, overexpression of CXCL9 and CXCL10 is associated with a higher number of tumor-infiltrating lymphocytes and improved survival, e.g., in breast, ovarian, colon, lung, and several other cancers." (PMID 31482487, 2019). "During this complex process, overexpression of chemokines (such as CXCL10) may be involved in a positive loop of sustained tumor-associated inflammation." (PMID 30847302, 2019). "CXCL10 was associated with tumor cell motility and metastasis in various type of cancer." (PMID 30847302, 2019).
tumor (continued). "E7046 + E7777 treatment activated the innate immune system which led to an “inflamed” TME evidenced by expression of genes encoding Ccl5/RANTES, macrophage inflammatory protein-1α (MIP-1α/Ccl3), Cxcl9, Cxcl10, and Cxcl11, previously found associated with tumor destruction." (PMID 28920002, 2017). "For example, in a colorectal cancer model neuroendocrine differentiation may induce the infiltration of tumour-associated macrophages (TAMs) attracted by CXCL-10 and CXCL-11 leading to enhanced tumour cell proliferation and invasion." (PMID 29157300, 2017). "Moreover, CXCL10 is expressed in basal tumors as compared with ER+ tumors, being associated with a higher tumor grade and a poor prognosis of breast cancer." (PMID 26752044, 2016). "Moreover, alterations in CXCL10 expression levels have been associated with inflammatory diseases including infection, immune dysfunction and tumor development." (PMID 28018321, 2016). "Notably, the CXCL10-driven T cell response is associated with simultaneous upregulation of both activation and exhaustion markers, indicating a robust but transient effector state within the tumor microenvironment." (PMID 41665072, 2026). "Future mechanistic studies are warranted to define how MTAP deficiency alters tumor glutamate metabolism to suppress CXCL10 expression, and whether CB-839-mediated upregulation of CXCL10 is sufficient to restore T cell infiltration and activation in MTAP-deficient tumors." (PMID 41246302, 2025). "Therefore, this study hypothesized that the increase in CXCR3+ T cells in the blood of treatment-resistant patients might be caused by a decrease in the activation of CXCL9 and CXCL10 inside the tumor microenvironment." (PMID 39273452, 2024). "In this study, we improved the virus-induced tumor immunogenicity of recombinant Semliki Forest virus (rSFV)-based replicon particles by encoding immunogenic cytokines such as C-X-C motif chemokine ligand 10 (CXCL10), FMS-like tyrosine kinase 3 ligand (Flt3L), or interferon-gamma (IFN-ƴ)." (PMID 38425844, 2024). "Also, CXCL10+ cDCs might be isolated as a potential pool for loading tumor-associated antigens for cell-based therapy, which warrants further investigation." (PMID 39104420, 2024). "Therefore, IFNγ/CXCL10 can be linked to the anti-tumor immune response." (PMID 37445941, 2023). "CXCL10 may be associated with tumor development and metastasis." (PMID 36207693, 2022). "Additionally, IFN-γ production by Th1 cells induces secretion of CXCL9 and CXCL10 by tumor-associated macrophages (TAM) and cancer-associated fibroblasts (CAF) as well as tumor cells present in the TME that promote tumor-effector T cell infiltration in melanoma patients." (PMID 35008422, 2022). "Besides signatures of cell cycle acceleration, epithelial–mesenchymal transition and B-cell depletion, we discover an inflammation-associated signature, featured by the chemokine CXCL10, is in fact secreted by tumor-associated macrophages using single-cell RNA sequencing data." (PMID 35433690, 2022). "Moreover, high CXCL10 mRNA expression is associated with a better tumor response to pCRT in LARC patients and may predict the outcome of pCRT in this malignancy." (PMID 26359356, 2015). "Quantitative real-time polymerase chain reaction analysis showed that PCD@Cu significantly upregulated the expression of Cgas, CCL5, and CXCL10 in tumor tissues, indicating that PCD@Cu activated the cGAS/STING pathway." (PMID 41424843, 2026). "Mechanistically, OLIG2 recruited HDAC7 to repress CXCL10 transcription, inducing STAT3 activation in tumor-associated macrophages (TAMs) and decreasing CD8+ T cell infiltration and activation." (PMID 41591814, 2026). "In contrast, CXCL10 induced a similar level of lymphocyte infiltration, but tumor growth was significantly restricted." (PMID 41399390, 2026).